SLC35B2 (solute carrier family 35 member B2)
Description:
Probably functions as a 3'-phosphoadenylyl sulfate:adenosine 3',5'-bisphosphate antiporter at the Golgi membranes. Mediates the transport from the cytosol into the lumen of the Golgi of 3'-phosphoadenylyl sulfate/adenosine 3'-phospho 5'-phosphosulfate (PAPS), a universal sulfuryl donor for sulfation events that take place in that compartment.
Synonyms: PAPST1; UGTrel4; HLD26; SLL
Tractability: Antibody: UniProt predicts a signal peptide or a membrane-spanning region. PROTAC: ubiquitination databases record sites on it; its protein half-life has been measured.
Gene: Protein-coding gene on chromosome 6 (44,254,096 to 44,257,890, reverse strand). Ensembl gene ENSG00000157593.
Subcellular location: Golgi apparatus membrane
Subcellular location (Human Protein Atlas): Vesicles
Pathways (Reactome):
Metabolism: Transport and metabolism of PAPS
Transport of small molecules: Transport of nucleotide sugars
Gene Ontology:
Molecular function: 3'-phosphoadenosine 5'-phosphosulfate transmembrane transporter activity; protein binding
Biological process: 3'-phosphoadenosine 5'-phosphosulfate transport; chondroitin sulfate proteoglycan biosynthetic process; positive regulation of canonical NF-kappaB signal transduction; 5'-adenylyl sulfate transmembrane transport; 3'-phospho-5'-adenylyl sulfate transmembrane transport; transmembrane transport
Cellular component: Golgi apparatus; Golgi membrane; membrane; trans-Golgi network
Genetic constraint (gnomAD): Loss-of-function variants: 19 observed, 39.32 expected, observed/expected ratio (o/e) 0.48, 90% interval 0.34 to 0.71. The upper end of that interval is the gene's LOEUF score, 0.71, which puts it in group 2 of 6, group 1 being the genes least tolerant of losing a copy. Missense variants: 633 observed, 576.09 expected, observed/expected ratio (o/e) 1.1, 90% interval 1.03 to 1.17. Synonymous variants: 277 observed, 239.24 expected, observed/expected ratio (o/e) 1.16, 90% interval 1.05 to 1.28.
Homologues: Orthologues: chimpanzee SLC35B2 (100% identical), macaque SLC35B2 (99% identical), dog SLC35B2 (97% identical), pig SLC35B2 (95% identical), mouse Slc35b2 (92% identical), rat Slc35b2 (92% identical), guinea pig SLC35B2 (90% identical), rabbit SLC35B2 (90% identical), tropical clawed frog slc35b2 (70% identical), zebrafish slc35b2 (68% identical), Drosophila melanogaster sll (46% identical), Caenorhabditis elegans pst-1 (39% identical). Paralogues in human: SLC35B1 (24% identical), SLC35B3 (19% identical), SLC35B4 (11% identical).
Diseases named in the same sentence as SLC35B2 in open-access papers:
SLC35B2 is named in the same sentence as 17 diseases in open-access papers, as found by Europe PMC text mining. Sharing a sentence is not in itself a finding about the gene and the disease. The quoted sentences say what the papers report.
viral infection (2 papers, 2022 to 2025). "Therefore, although both SLC35B2 and B3GAT3 are involved in HS synthesis, we chose to use B3GAT3 KO cells in our analysis to more specifically evaluate the role of HS in viral infection." (PMID 40548749, 2025). "It has been described as an attractive therapeutic target to prevent viral infections, as SLC35B2 knockout did not affect the viability of normal cells, but prevented viral infection due to decreased sulfation of proteins or proteoglycans essential for viral entry." (PMID 35798875, 2022).
chondrodysplasia (1 paper, 2022). "Homozygous mutations in SLC35B2 were found in two patients presenting with chondrodysplasia (disrupted growth of cartilage), intellectual disability, and hypomyelination on brain MRI." (PMID 36003149, 2022).
colorectal cancer (1 paper, 2022). A primary or metastatic malignant neoplasm that affects the colon or rectum. "However, SLC35B3—a paralog of SLC35B2—is expressed in the colon and might compensate for the loss of SLC35B2 activity in colorectal cancer." (PMID 35798875, 2022).
melanoma (1 paper, 2022). A malignant, usually aggressive tumor composed of atypical, neoplastic melanocytes. "In contrast, upon treatment with Vemurafenib, SLC35B2 knockout clones of both cell types proliferated significantly slower, indicating that loss of SLC35B2 re-sensitized YAP5SA melanoma cells to Vemurafenib in vitro." (PMID 35798875, 2022). "The SLC35B2 knockout-dependent loss of HS expression was associated with re-sensitization of YAP1-activated melanoma cells toward MAPKis in vitro and in vivo." (PMID 35798875, 2022). "SLC35B2 expression correlates with tumor progression, and its loss decreases heparan sulfate expression, reduces receptor tyrosine kinase activity, and sensitizes resistant melanoma cells to BRAF inhibition in vitro and in vivo." (PMID 35798875, 2022). "Interestingly, high SLC35B2 expression in melanoma was significantly associated with shorter PFI in BRAFV600E mutant, but not BRAF wildtype metastatic melanoma." (PMID 35798875, 2022). "Thus, loss of SLC35B2 sensitizes YAP5SA melanoma cells to Vemurafenib in vitro and in vivo." (PMID 35798875, 2022). "The microRNA miR-22 can act as a tumor suppressor, is downregulated in many cancers including melanoma, and has been shown to suppress mRNA levels of SLC35B2." (PMID 35798875, 2022). "In summary, we identify SLC35B2 as a novel vulnerability of YAP1-driven MAPKi resistance in melanoma through limiting heparan sulfation and thereby compensatory RTK activation." (PMID 35798875, 2022). "We sought to identify the underlying mechanism by which loss of SLC35B2 and reduced HS levels re-sensitize YAP5SA melanoma cells to Vemurafenib." (PMID 35798875, 2022). "In YAP1-activated melanoma cells, SLC35B2 knockout abrogated HS surface expression and limited activity of YAP1-stimulated RTKs including ERBB3, EGFR, and AXL." (PMID 35798875, 2022). "In summary, we describe high YAP1/TAZ activity as a molecular driver of MAPKi-resistant MITFlow/AXLhigh melanomas and identify SLC35B2 as a single target for overcoming broad compensatory pathway activation through limiting RTK activity." (PMID 35798875, 2022). "In melanoma, however, this association is only significant for BRAFV600E mutant tumors, suggesting a role of SLC35B2 particularly in the context of MAPKi treatment which represents a standard treatment in advanced BRAFV600 mutant, but not BRAF wildtype melanoma." (PMID 35798875, 2022). "Interestingly, treatment of SKMEL28-YAP5SA cells with high doses of UFH or the LMWH nadroparin efficiently suppressed ERBB3 and AXL activity, comparably to loss of SLC35B2, further supporting HS dependency of ERBB3 and AXL signaling in melanoma cells." (PMID 35798875, 2022). "sgRNAs targeting EGFR or SLC35B2, respectively, were depleted only in YAP5SA cells treated with Vemurafenib, but were not substantially changed in untreated YAP5SA cells or parental melanoma cells (EV)." (PMID 35798875, 2022). "We then compared proliferation of these SLC35B2 knockout clones with YAP5SA melanoma cells transduced with a non-targeting (nt) sgRNA." (PMID 35798875, 2022). "In addition, expression of EXT1, but not SLC35B2, was positively correlated with the YAP1/TAZ score in the TCGA cohort of BRAF mutant melanoma, suggesting that EXT1 is a YAP1/TAZ target." (PMID 35798875, 2022). "While SLC35B2 knockout sensitized YAP1-activated melanoma cells toward Vemurafenib treatment, it did not completely stop melanoma cell proliferation, comparable to the strong, but limited effect of Vemurafenib single treatment on BRAFV600 mutant melanoma cells without YAP1 activation." (PMID 35798875, 2022).
uveal melanoma (1 paper, 2022). A melanoma derived from melanocytes of the uveal tract. "Furthermore, SLC35B2 was highly expressed in solid tumors, with the highest expression in cutaneous and uveal melanoma, and low expression in hematological malignancies." (PMID 35798875, 2022).
infection (8 papers, 2017 to 2025). The state of being infected such as from the introduction of a foreign agent such as serum, vaccine, antigenic substance or organism. "The results obtained for SLC35B2 knockout variants after infection with VSV WT or VSV-GP variants are stronger but in line with those generated for sodium chlorate treated 293T WT and ΔDAG1 cells." (PMID 34648606, 2021). "In HeLa-N cells, KO of SLC35B2 resulted in reduced susceptibility to SAFV-3 infection." (PMID 41397982, 2025). "Reconstituted SLC35B2 in HeLaΔSLC35B2 cells regained susceptibility to PRV3M and PRV2P infection, with 3.9 log TCID50/ml and 2.4 log TCID50/ml increase in viral titres, respectively." (PMID 37143369, 2023). "Knocking out TPST2 and SLC35B2 conferred resistance to infection which was reverted back upon rescue with introduction of sgRNA resistant cDNA of these genes." (PMID 37794981, 2023). "To determine whether sulfated GAGs or sulfated proteins are critical for SAFV-3 infection, we established SLC35B2 KO and EXT1 KO HeLa-N cell lines (referred to as HeLaN-∆SLC and HeLaN-∆EXT1, respectively)." (PMID 41397982, 2025). "Enzymatic removal of cell surface HS by heparinase treatment and genetic ablation of HS biosynthesis genes, SLC35B2, exostosin-1, N-deacetylase/N-sulfotransferase I and beta-1,3-glucuronyltransferase 3, significantly reduced infection with multiple genetically distinct PRV species." (PMID 37143369, 2023). "In addition to CDK4 and IFITM proteins, targeting of SLC35B2 in both SARS-CoV-2 and OC43 Vero E6 screens increased resistance to infection, suggesting that it is a pan-HCoV host factor in this cell line." (PMID 35086559, 2022). "Absence of SLC35B2, B4GALT7 also led to reduced dsRNA transfectability, SINV infectivity and infection induced cell death." (PMID 37794981, 2023). "Indeed, studies demonstrated that other molecules, such as SLC35B2 and B3GAT3, are related to the successful entry of EV-A71, as their knockout but not hSCARB-2 decreased EV-A71 infection." (PMID 36992493, 2023).
cancer (3 papers, 2012 to 2022). A tumor composed of atypical neoplastic, often pleomorphic cells that invade other tissues. "Across cancers, high SLC35B2 expression is associated with shorter PFI." (PMID 35798875, 2022). "We highlight SLC35B2 whose strong overexpression in primary tumors and metastases compared to normal tissue makes it an attractive anti-cancer target." (PMID 35798875, 2022). "Other miR-143 responsive genes with a miR-143 seed site in their 3'UTR were SEMA5A, SLC35B2 and KLF5 which have all been shown to be up-regulated in cancers and to promote cell proliferation." (PMID 22691140, 2012). "In contrast to EGFR, SLC35B2 has not been investigated in the context of cancer and drug resistance." (PMID 35798875, 2022). "SLC35B2 has not been evaluated as a target for anti-cancer therapies." (PMID 35798875, 2022). "We found a trend toward lower SLC35B2 expression in YAP5SA cell lines compared to controls, indicating that SLC35B2 might not be a direct YAP1 target and molecular regulators independent from YAP1/TAZ might drive SLC35B2 expression in cancer." (PMID 35798875, 2022). "As SLC35B2 has not been studied systematically in the context of cancer, we further assessed SLC35B2 expression in SKMEL28-YAP5SA and A375-YAP5SA cell lines and across human tumors using pancancer and normal tissue transcriptome data from TCGA and Genotype-Tissue Expression (GTEx) datasets." (PMID 35798875, 2022).
tumor (2 papers, 2022 to 2025). "Similar to the observations in vitro, loss of SLC35B2 significantly decreased tumor growth and improved survival compared with controls upon treatment with Vemurafenib." (PMID 35798875, 2022). "Importantly, high SLC35B2 expression across tumor entities was associated with significantly worse overall survival, disease-specific survival, and shorter progression-free interval (PFI), further highlighting its potential clinical relevance." (PMID 35798875, 2022). "It is thus tempting to speculate that an RTK spectrum beyond ERBB3, EGFR, and AXL might be affected by SLC35B2 levels, depending on individual tumor type and treatment context." (PMID 35798875, 2022). "Interestingly, SLC35B2 was higher expressed in solid tumors compared to normal tissue, and its expression increased from primary to recurrent and to metastatic solid tumors, correlating with tumor progression." (PMID 35798875, 2022).
genetic disorders (1 paper, 2020). "So far, no human genetic disorders have been linked to mutations in SLC35B2 and SLC35B3 genes, but cartilage defects have been reported in slc35b2 null zebrafish mutants." (PMID 32295296, 2020).
SLC35B2 also shares sentences with these, for which no sentence is quoted: asthma (2 papers); Bell's palsy (1); diabetes (1); hematological malignancies (1); leukodystrophy (1); medulloblastoma (1); metastatic melanoma (1); prediabetes (1).